AIRE (autoimmune regulator)
Diseases named in the same sentence as AIRE in open-access papers (continued):
Sharing a sentence is not in itself a finding about the gene and the disease.
Infertility (4 papers, 2017 to 2025). "Here, we focus on the potential associations of AIRE deficiency with infertility as well as the possible pathogenesis, providing insight into the significance of AIRE in the development of infertility." (PMID 33679804, 2021). "Since the depletion of AIRE is responsible for infertility, a large number of studies have attempted to quantify the effects of AIRE deficiency on infertility." (PMID 33679804, 2021). "Additionally, emerging evidence has demonstrated that AIRE deficiency is also related to infertility, one of the comorbidities associated with APECED." (PMID 33679804, 2021). "Many studies have reported that AIRE deficiency may result in infertility in females or males, suggesting that the loss of AIRE is one of the most determinant factors of infertility." (PMID 33679804, 2021). "The pathology of infertility in AIRE-deficient mice displays sex differences." (PMID 33679804, 2021). "Therefore, SVS2 impairment is closely associated with infertility mediated by AIRE loss." (PMID 33679804, 2021). "Overall, studies using these mouse models lacking AIRE point to a critical role played by AIRE in maintaining normal reproductive function, and female mice with deletion of AIRE suffer from high rates of infertility." (PMID 33679804, 2021).
uveitis (4 papers, 2013 to 2024). An inflammatory process affecting a part of or the entire uvea. "It is of note that uveitis in AIRE−/− mice targets the IRBP antigen, as mice deficient in IRBP fail to develop retinal disease." (PMID 24015215, 2013). "In the present study, we characterized and compared three distinct models of uveitis: the “classical” EAU model induced by immunization and two spontaneous models in IRBP TCR transgenic R161H mice and AIRE−/− mice." (PMID 24015215, 2013). "However, the uveitis in R161H and AIRE−/− mice has not been well characterized." (PMID 24015215, 2013).
viral diseases (4 papers, 2023). "Collectively, these results suggest that the human alternative NF-κB pathway controls AIRE expression in mTECs and that human inborn errors of this pathway thereby underlie the development of AAN-I-IFNs and the resulting predisposition to viral infection." (PMID 37938781, 2023). "Autoantibodies neutralizing type I IFNs due to rare inborn errors of autoimmune regulator (AIRE)–driven T cell tolerance were discovered in 2006, but not initially linked to any viral disease." (PMID 36719370, 2023).
alopecia areata (3 papers, 2015 to 2024). Loss of scalp and body hair involving microscopically inflammatory patchy areas. "Hair loss in DS is typically associated to Alopecia areata, an autoimmune condition in which hair follicles are attacked by the immune cells, likely secondary to complex immune dysregulation caused by trisomy of chromosome 21 genes, such as Autoimmune Regulator—AIRE— and 4 interferon receptor genes." (PMID 37670378, 2023).
autoimmune thyroid disease (3 papers, 2019 to 2024). Inflammatory disease of the thyroid gland due to autoimmune responses leading to lymphocytic infiltration of the gland. "We herein report a novel missense mutation in the AIRE gene in a Chinese boy with APS-1 accompanied by atrophic spleen and autoimmune thyroiditis." (PMID 32358377, 2020). "In contrast, males’ relative protection against CNS and thyroid autoimmunity may be due to the varying effects of sex hormones on the expression of the autoimmune regulator (AIRE)." (PMID 39001953, 2024).
breast carcinoma (3 papers, 2018 to 2025). "Concordantly, AIRE silencing suppressed colony formation, tumorigenesis, and upregulation of stemness-associated genes and breast cancer stem cell markers." (PMID 37369642, 2023).
dry eye (3 papers, 2013 to 2021). "We established mice deficient in the autoimmune regulator (Aire) gene as a model for autoimmune-mediated aqueous-deficient dry eye." (PMID 24068863, 2013). "Mice deficient in the autoimmune regulator (Aire) gene developed spontaneous, CD4+ T cell-mediated exocrinopathy and aqueous-deficient dry eye that were associated with loss of nerves innervating the cornea and lacrimal gland." (PMID 28926640, 2017). "Nevertheless, a mouse model of AIRE gene deficiency showed that deficient mice experienced loss of nerve innervation in the cornea and the lacrimal gland, which was associated with spontaneous, CD4+ T-cell mediated exocrinopathy and aqueous-deficient dry eye." (PMID 33413189, 2021).
myasthenia gravis (3 papers, 2012 to 2024). Myasthenia gravis (MG) is a rare, clinically heterogeneous, autoimmune disorder of the neuromuscular junction characterized by fatigable weakness of voluntary muscles. "In inborn or acquired AIRE deficiency, seen in APS-I patients and myasthenia gravis (MG) patients with thymoma respectively, expression of IFN-I will be out of control, leading to dysregulation of the feedback loop and probably high local levels of these cytokines in the thymus." (PMID 38455040, 2024).
systemic sclerosis (3 papers, 2020 to 2023). A chronic disorder, possibly autoimmune, marked by excessive production of collagen which results in hardening and thickening of body tissues. "Several studies addressed AIRE gene polymorphisms in RA patients, and one study tackled it in patients with progressive systemic sclerosis (PSS)." (PMID 34621318, 2021).
atherosclerosis (2 papers, 2020 to 2021). A disease characterized by the build-up of fatty material and calcium deposition in the arterial wall resulting in partial or complete occlusion of the arterial lumen. "Herein we crossed Aire- and apolipoprotein E (Apoe)-deficient (Aire−/−Apoe−/−) mice to test whether lack of AIRE would increase peripheral ApoB-reactive effector T cell numbers and functions and increase atherosclerosis." (PMID 35097028, 2021). "In conclusion, our data suggests that AIRE is not involved in regulating thymic expression of ApoB or atherosclerosis." (PMID 35097028, 2021).
autoimmune hypoparathyroidism (2 papers, 2022 to 2025). An autoimmune form of hypoparathyroidism. "Although direct epigenetic studies in autoimmune hypoparathyroidism are limited, AIRE function is inherently chromatin dependent." (PMID 41465179, 2025). "Autoimmune hypoparathyroidism can occur as an isolated endocrinopathy or as a part of the autoimmune polyglandular syndrome type I (APS-1), a genetic disorder caused by mutations in the autoimmune regulator (AIRE) gene." (PMID 36153665, 2022).
Enteropathy (2 papers, 2023 to 2025). "As AIRE is suggested to play a role in the development of Tregs, these cells might contribute to enteropathy as this manifestation is common in patients with reduced T reg function." (PMID 37235056, 2023).
IPEX syndrome (2 papers, 2023 to 2025). "APS-1 and IPEX syndrome are monogenic disorders, caused by mutations in the autoimmune regulator (AIRE) and forkhead box protein P3 (FOXP3) genes, respectively." (PMID 36980146, 2023).
male infertility (2 papers, 2021 to 2025). The inability of the male to effect fertilization of an ovum after a specified period of unprotected intercourse. "Thus, in this review, we specifically focus on the relationship between AIRE deficiency and female and male infertility in mice." (PMID 33679804, 2021).
neuropathy (2 papers, 2020 to 2021). A disorder affecting the nervous system that manifests with pain, tingling, numbness, and/or muscle weakness. "AIRE-deficient mice models of corneal and lacrimal gland neuropathy that were found to exhibit autoimmune exocrinopathy strengthen our theory that APS-1 may inherently cause neuropathy and therefore lead to APS-1 keratopathy secondarily." (PMID 33413189, 2021).
oral squamous cell carcinoma (2 papers, 2020 to 2024). "This study aimed to clarify the role of AIRE in the pathogenesis of oral squamous cell carcinoma (OSCC)." (PMID 32012175, 2020). "Cooperative upregulation of ICAM1 gene transcription by ETS-1 and autoimmune regulator (AIRE) in human oral squamous cell carcinoma cells, and by ETS-1 and signal transducer and activator of transcription 1 (STAT 1) in human HEK293 and monkey COS-1 kidney cell lines are also reported." (PMID 38984117, 2024).
prostate tumor (2 papers, 2019). "In addition, AIRE is found highly expressed in PC-3 cells and functions as prostate tumor promoter gene in vivo." (PMID 31641374, 2019).
psoriasis (2 papers, 2019 to 2024). An autoimmune condition characterized by red, well-delineated plaques with silvery scales that are usually on the extensor surfaces and scalp. "Instead we found that AIRE mediates expression of IRGs in activated RA FLS, in particular a set of genes which have been associated with psoriasis skin lesions." (PMID 31275320, 2019).
retinal degeneration (2 papers, 2013 to 2020). Degeneration of the retina. "AIRE−/− mice lacked anterior uveitis and the characteristic feature of their disease was a relatively low-grade but multi-focal retinal inflammation along with severe choroiditis, that subsequently led to retinal degeneration." (PMID 24015215, 2013).
AIDS (1 paper, 2021). A syndrome resulting from the acquired deficiency of cellular immunity caused by the human immunodeficiency virus (HIV). "Mutations in AIRE predispose also to PA similar to the other AIDs manifested in the syndrome." (PMID 33505716, 2021).
alcoholism (1 paper, 2018). "Stratification analyses of sex, age, smoking, and alcoholism suggested that the rs878081 polymorphism of the AIRE gene increased RA risk among non-smokers." (PMID 30403260, 2018).
autoimmune retinopathy (1 paper, 2021). An autoimmune disease characterized by sudden onset of photopsias and scotomata in patients with no family history of retinitis pigmentosa, followed by visual field and central vision loss. "Here we report a 2-year-old Japanese girl with an AIRE gene mutation who developed APAH with ALF, preceded by autoimmune retinopathy associated with anti-recoverin antibody before major symptoms suggested a diagnosis of APECED." (PMID 34122451, 2021).
autoimmune uveitis (1 paper, 2013). An autoimmune form of uveitis (disease). "In addition to R161H mice, spontaneous autoimmune uveitis develops in mice deficient in the AIRE (AutoImmune Regulator) gene." (PMID 24015215, 2013).
celiac disease (1 paper, 2021). An autoimmune genetic disorder with an unknown pattern of inheritance that primarily affects the digestive tract. "Most of the chronic HypoPT cases were post-neck surgical for thyroid goiter or tumor, followed by 2 probable autoimmune HypoPT cases (no AIRE gene mutations were detected, but one patient also had chronic autoimmune thyroiditis and another had celiac disease), and 2 idiopathic HypoPT cases." (PMID 34627337, 2021).
cognitive decline (1 paper, 2021). "Furthermore, DMRs annotated to MORN4, AIRE, LY6G5C, and PRRT1 were identified for both rates of cognitive decline as measured by the slopes of mPACCdigit/mPACCtrailsB and CDR-SB." (PMID 34654479, 2021).
Crohn disease (1 paper, 2011). A gastrointestinal disorder characterized by chronic inflammation involving all layers of the intestinal wall, noncaseating granulomas affecting the intestinal wall and regional lymph nodes, and transmural fibrosis. "We found that a GC-only eQTL for AIRE (rs762421) was associated with risk of the Crohn's disease." (PMID 21750684, 2011).
diabetes insipidus (1 paper, 2021). A disorder characterized by excretion of large amounts of urine, accompanied by excessive thirst. "This case suggests that diabetes insipidus is a rare component of APS-1 and expands the variety of mutations on AIRE gene." (PMID 34344344, 2021).
Fever (1 paper, 2025). Body temperature elevated above the normal range.
glioma (1 paper, 2024). A benign or malignant brain and spinal cord tumor that arises from glial cells (astrocytes, oligodendrocytes, ependymal cells). "Inhibition of AIRE expression enables immunotherapy of Diffuse Midline Glioma." (PMID 39606441, 2024).
lupus nephritis (1 paper, 2021). Glomerulonephritis in the context of systemic lupus erythematosus. "In addition, AIRE rs2075876 AA was more common in patients with lupus nephritis (LN) under the recessive model (100% for AA versus 69.3% for AG+GG) with a p value of 0.032." (PMID 34621318, 2021).
lymph node metastasis (1 paper, 2020). "Next, we examined whether AIRE expression was associated with clinicopathological parameters, including the differentiation grade, invasion pattern, lymph node metastasis, and level of inflammatory cell infiltration in the cancer stroma." (PMID 32012175, 2020).
Lymphadenopathy (1 paper, 2018). Enlargement (swelling) of a lymph node. "Lymphadenopathy is generally associated with prostate cancer metastasis and as predictable lymph nodes isolated were bigger in size due to inflammation in AIRE+/+ mice as compared to lymph nodes from AIRE−/− mice 35,36." (PMID 29795364, 2018). "AIRE by inducing malignancy factor IL-6 leads to more of inflammation and lymphadenopathy in AIRE+/+ mice; however, a small benign tumor is observed in AIRE−/− mice." (PMID 29795364, 2018). "Subcutaneous mouse model of prostate cancer revealed AIRE+/+ mice forming a palpable tumor and presents lymphadenopathy however, only a small benign tumor is observed in AIRE−/− mice and lymph nodes appear normal in size." (PMID 29795364, 2018).
lymphoma (1 paper, 2021). A malignant (clonal) proliferation of B- lymphocytes or T- lymphocytes which involves the lymph nodes, bone marrow and/or extranodal sites. "An Aire-deficient mouse model with impairment of the hematologic development of the monocyte linage developed marginal zone B cell (MZB) lymphoma, indicating an exaggerated activation of B cells in AIRE-deficient mice which increased with age." (PMID 34572460, 2021).
myositis (1 paper, 2025). "We designed an ELISA with full-length AIRE protein to evaluate AIRE reactivity in a validation cohort that consisted of serum samples from 26 anti-Mi2 autoantibody-positive DM patients, 44 myositis patients with other MSAs or IBM, and 63 healthy comparators." (PMID 40568090, 2025). "Exploring the muscle-specific and systemic effects of this reactivity could reveal how the dysregulation of target autoantigens like Mi2 and AIRE interact to drive the development of myositis and other autoantibody-mediated diseases." (PMID 40568090, 2025). "Given that nearly all anti-Mi2 autoantibody-positive patients were also anti-AIRE-positive, it was not feasible to conduct a comparative analysis of the clinical characteristics between anti-AIRE-positive and anti-AIRE-negative patients within anti-Mi2 autoantibody-positive myositis." (PMID 40568090, 2025).
oophoritis (1 paper, 2021). Inflammation of the ovary, generally caused by an ascending infection of organisms from the endocervix. "Importantly, the deletion of AIRE leads to severe oophoritis and age-dependent depletion of follicular reserves and causes altered embryonic development in female mice." (PMID 33679804, 2021).
ovarian tumors (1 paper, 2020). "In this context, the observed up-regulation of AIRE mRNA expression in ovarian tumors associated with anti-Yo PCD as compared to other ovarian tumors is puzzling." (PMID 32655545, 2020).
pneumonitis (1 paper, 2021). An inflammatory process affecting the lung parenchyma. "APECED is caused by loss-of-function mutations in the autoimmune regulator (AIRE) gene, which lead to impaired central immune tolerance and autoimmune organ destruction including pneumonitis, an underrecognized, life-threatening complication." (PMID 34401309, 2021).
polyarticular arthritis (1 paper, 2017). An arthritis affecting five or more separate joints.
prostate carcinoma (1 paper, 2018). A carcinoma that arises from epithelial cells of the prostate gland. "Excavating the intricate role of AIRE in androgen-dependent and -independent prostate cancer opened new avenues in the field of molecular regulation of AIRE and the causation." (PMID 29795364, 2018). "AIRE regulates T regulatory cells (Tregs) isolated originally from prostate cancer, which may get co-opted by tumors developing in the organ posing its immunoregulatory role in prostate cancer." (PMID 29795364, 2018). "Moreover, AIRE overexpression in PC3 prostate cancer cells resulted in inhibition of drug-induced cell death thereby promoting cell survival and it also enhances the invasiveness of cancer cells which is a pre-requisite phenomenon leading to metastasis." (PMID 29795364, 2018).
thymic epithelial tumors (1 paper, 2023). "Our results demonstrated that thymic cortical and medullary epithelial markers including β5t, PRSS16, cathepsin V, and AIRE could be used as ancillary markers in the diagnosis and prognosis of thymic epithelial tumors." (PMID 36797681, 2023).
uterine infection (1 paper, 2022). "The transcription factor, autoimmune regulator (AIRE), was identified as an inhibited discordant upstream regulator of pregnancy regulated genes following uterine infection." (PMID 35358206, 2022). "A total of 14 predicted upstream regulators were identified only in healthy cows (P < 0.05), while five unique predicted upstream regulators were identified only in cows after uterine infection, including the inhibition of ISG15 and AIRE, and activation of DUSP1, NFKBIA, and PF4 (P < 0.05)." (PMID 35358206, 2022).